ANKS4B (ankyrin repeat and sterile alpha motif domain containing 4B)
Description:
As part of the intermicrovillar adhesion complex/IMAC plays a role in epithelial brush border differentiation, controlling microvilli organization and length. Plays a role in assembly of the complex. May play a role in cellular response to endoplasmic reticulum stress (By similarity).
Synonyms: Harp; FLJ38819
Tractability: Antibody: its Gene Ontology location is reachable by antibodies, with medium confidence.
Gene: Protein-coding gene on chromosome 16 (21,233,699 to 21,253,850, forward strand). Ensembl gene ENSG00000175311.
Subcellular location: Cell projection, microvillus
Subcellular location (Human Protein Atlas): Cytosol; Nucleoplasm
Gene Ontology:
Molecular function: protein binding; myosin binding
Biological process: brush border assembly; protein localization to microvillus; protein-containing complex assembly; response to endoplasmic reticulum stress
Cellular component: brush border; microvillus; stereocilia ankle link; endoplasmic reticulum membrane; plasma membrane; plasma membrane bounded cell projection
Genetic constraint (gnomAD): Loss-of-function variants: 29 observed, 29.83 expected, observed/expected ratio (o/e) 0.97, 90% interval 0.72 to 1.33. The upper end of that interval is the gene's LOEUF score, 1.33, which puts it in group 5 of 6, group 1 being the genes least tolerant of losing a copy. Missense variants: 473 observed, 519.53 expected, observed/expected ratio (o/e) 0.91, 90% interval 0.84 to 0.98. Synonymous variants: 179 observed, 203.48 expected, observed/expected ratio (o/e) 0.88, 90% interval 0.78 to 1.
Homologues: Orthologues: chimpanzee ANKS4B (98% identical), macaque ANKS4B (95% identical), pig ANKS4B (88% identical), rabbit ANKS4B (87% identical), guinea pig ANKS4B (85% identical), mouse Anks4b (83% identical), rat Anks4b (82% identical), dog ANKS4B (77% identical), tropical clawed frog anks4b (53% identical), zebrafish anks4b (48% identical), Drosophila melanogaster Sans (35% identical). Paralogues in human: USH1G (45% identical).
Diseases named in the same sentence as ANKS4B in open-access papers:
ANKS4B is named in the same sentence as 8 diseases in open-access papers, as found by Europe PMC text mining. Sharing a sentence is not in itself a finding about the gene and the disease. The quoted sentences say what the papers report.
Colon Cancer (2 papers, 2021 to 2023). "In addition, the loss of brush-limbic proteins involved in cell polarity in colon cancer is important for tumor development, suggesting that ANKS4B may influence the occurrence and development of colon cancer." (PMID 34552622, 2021).
hepatoma (1 paper, 2020). "As ANKS4B is abundantly expressed in hepatoma cells, we then investigated whether ANKS4B confers an antiviral activity in Huh7 cells." (PMID 32793175, 2020). "As ANKS4B has been reported to be abundantly expressed in liver, kidney, small intestine, and colon, we examined whether ZIKV infection had an impact on ANKS4B expression in a hepatoma cell line, Huh7." (PMID 32793175, 2020).
virus infection (1 paper, 2020). "At 24, 48, and 72 h p.i., the mRNA levels of ANKS4B in the ZIKV-infected cells were about half of those in the mock-infected cells, consistent with our microarray data.To be noted, the mRNA level of ANKS4B was extremely low at 72 h p.i., probably due to the cytopathic effect of viral infection." (PMID 32793175, 2020).
vitiligo (1 paper, 2025). Generalized well circumscribed patches of leukoderma that are generally distributed over symmetric body locations and is due to autoimmune destruction of melanocytes. "Finally, we obtained ten matched genes (GP1BA, ANKS4B, CCDC87, CA8, HLA‐DOB, RHEBL1, NLRP7, GZMH, HERPUD1, and MAP2K1) as a vitiligo‐gene signature (VGS)." (PMID 40974370, 2025).
ZIKV infection (1 paper, 2020). "As the ER stress induced by ZIKV infection is associated with autophagy, we explored whether ANKS4B has an impact on the autophagy induced by ZIKV." (PMID 32793175, 2020). "At 24 h p.i., the levels of HNFs in A549 or Huh7 cells were reduced by 1.3–2.2 fold compared to mock-infected cells, suggesting that ZIKV infection downregulated the levels of HNFs, which further led to the decrease of ANKS4B." (PMID 32793175, 2020). "To explore how the expression of ANKS4B was downregulated by ZIKV infection, we carried out bioinformatics analysis to predict potential binding sites of transcription factors in its promoter region using an online software." (PMID 32793175, 2020). "Our data revealed that the expression of ANKS4B in cultured cells and in neonatal mice was downregulated by ZIKV infection." (PMID 32793175, 2020). "Our previous work revealed that in A549 cells, only one gene (ANKS4B) expression was decreased by more than twofold upon ZIKV infection." (PMID 32793175, 2020). "We found that the mRNA levels of ANKS4B decreased upon ZIKV infection in cultured cells (A549 and Huh7) and in neonatal mice." (PMID 32793175, 2020). "First, we demonstrated that the expression of ANKS4B was downregulated by ZIKV infection." (PMID 32793175, 2020). "Furthermore, we examined whether the ANKS4B expression was modulated by ZIKV infection in a neonatal mice model." (PMID 32793175, 2020). "Upon ZIKV infection, conversion of LC3-I to LC3-II in two ANKS4B-KO cells was significantly higher than control and ANKS4B-RES cells." (PMID 32793175, 2020). "It is worthwhile to point out, the expression of ANKS4B is gradually downregulated upon ZIKV infection, suggesting that ZIKV might have evolved some antagonism strategy against ANKS4B." (PMID 32793175, 2020). "Interestingly, the ANKS4B levels were significantly reduced in all ZIKV-infected tissues, indicating that ZIKV infection also led to in vivo downregulation of ANKS4B." (PMID 32793175, 2020). "In in vivo mice model, the ANKS4B expression was also downregulated upon ZIKV infection, implying that the modulation of ANKS4B by ZIKV is not cell specific." (PMID 32793175, 2020). "ANKS4B did not affect the viral entry step, but impaired the autophagy induced by ZIKV infection." (PMID 32793175, 2020).
tumor (3 papers, 2021 to 2023). "We analysed the methylation difference between tumour and normal tissues, and results manifested the most ERGs were hypermethylated within most malignancies, while ANKS4B was hypomethylated within most cancers types." (PMID 37815881, 2023). "The mean methylation of CpGs in two genes is hypomethylated in normal and hypermethylated at the terminal tumor regions (USP44 and SATB2); the opposite is true for three other genes (KRBA1, ANKS4B, and KDM8)." (PMID 37120552, 2023).
ANKS4B also shares sentences with these, for which no sentence is quoted: cancer (1 paper); cervical adenocarcinoma (1).